SPMAP2 (sperm microtubule associated protein 2)
Description:
May be involved (but not essential) in spermatogenesis.
Synonyms: CT56; THEG; THEG1
Tractability: No criterion of Open Targets' tractability assessment is met for any kind of drug.
Gene: Protein-coding gene on chromosome 19 (361,747 to 376,026, reverse strand). Ensembl gene ENSG00000105549.
Subcellular location: Nucleus
Subcellular location (Human Protein Atlas): Annulus; Cytosol; Equatorial segment; Principal piece
Gene Ontology:
Molecular function: protein binding
Biological process: chaperone-mediated protein complex assembly; spermatogenesis
Cellular component: nucleus
Genetic constraint (gnomAD): Loss-of-function variants: 38 observed, 40.72 expected, observed/expected ratio (o/e) 0.93, 90% interval 0.72 to 1.22. The upper end of that interval is the gene's LOEUF score, 1.22, which puts it in group 5 of 6, group 1 being the genes least tolerant of losing a copy. Missense variants: 560 observed, 496.62 expected, observed/expected ratio (o/e) 1.13, 90% interval 1.05 to 1.21. Synonymous variants: 225 observed, 191.3 expected, observed/expected ratio (o/e) 1.18, 90% interval 1.05 to 1.31.
Homologues: Orthologues: macaque SPMAP2 (87% identical), chimpanzee SPMAP2 (74% identical), pig SPMAP2 (70% identical), dog SPMAP2 (63% identical), rat Spmap2 (60% identical), mouse Spmap2 (59% identical), guinea pig SPMAP2 (57% identical), tropical clawed frog theg (19% identical), zebrafish spmap2 (18% identical), Drosophila melanogaster Theg (14% identical). Paralogues in human: SPMAP2L (21% identical).
Diseases named in the same sentence as SPMAP2 in open-access papers:
SPMAP2 is named in the same sentence as 2 diseases in open-access papers, as found by Europe PMC text mining. Sharing a sentence is not in itself a finding about the gene and the disease.
SPMAP2 shares sentences with these, for which no sentence is quoted: Infertility (1 paper); male infertility (1).